KRAS (KRas proto-oncogene, GTPase)
Diseases named in the same sentence as KRAS in open-access papers (continued):
Sharing a sentence is not in itself a finding about the gene and the disease.
metastatic disease (201 papers, 1993 to 2026). "We present a case of a 70-year-old woman with a history of moderately differentiated rectal adenocarcinoma treated with neoadjuvant radiotherapy and surgery who developed metastatic disease with a KRAS G12V mutation." (PMID 41853431, 2026). "Among patients presented with metastatic disease, the KRAS mutation was associated with significantly shorter survival, revealing its prognostic role among those with YO-CRC." (PMID 40940860, 2025). "The nomograms incorporated nine predictors: metastatic tumor count, cN stage, KRAS and BRAF mutation status, age, primary tumor location, neutrophil and platelet counts, and D-Dimer levels." (PMID 39991568, 2025). "KRAS mutation detection in LB for metastatic disease was associated with worse OS (median 14.5 vs. 31.3 months, HR = 2.7, 95%CI = 1.7–4.3, P < 0.001) but the OS difference was not significant in localized disease." (PMID 40247392, 2025). "Clinical outcomes varied among KRAS-mutated subtypes, with 7 cases developing metastatic disease and resistance to current treatment strategies, highlighting the need for subtype-specific diagnostic criteria and therapeutic strategies." (PMID 41375035, 2025). "KRAS mutations were detected in 64.6% (N = 148) of patients with metastatic disease, while only 16% (N = 13) of patients had localized disease." (PMID 40247392, 2025). "Most of the patients had metastatic disease, and all patients tested for KRAS mutations were KRAS wild type." (PMID 39410042, 2024). "When limited to patients with stage IV metastatic disease (n = 302), KRAS mutation remained significantly associated with OS (p = 0.034)." (PMID 38310130, 2024). "No meta-analyses have yet been published on the relationship between KRAS mutations and chemotherapy or timing of metastatic disease." (PMID 38667294, 2024). "One case report documented that KRAS mutations in metastatic tumors led to the use of anti-PD-1 therapy." (PMID 39552994, 2024). "Both primary and matched metastatic tumors were analyzed in four cases, in which the same KRAS (3/4) or PTEN (1/4) mutations were detected." (PMID 37626765, 2023). "More importantly, her primary and metastatic tumors were always governed by KRAS G12V mutations predicted to be neoantigens with strong affinity to HLA-A*11:01, while she did not have any other common immune-silent driver mutations in PAAD45." (PMID 37026827, 2023). "KRAS mutations were detected in 44 of 79 (56%) plasma samples at baseline, in 42 of 62 (63%) samples from patients with metastatic disease, and in two of 12 (17%) samples from patients with locally advanced disease (P = 0.004)." (PMID 37341038, 2023). "A higher number of KRAS mutations were observed in CRC brain metastatic tumours than in primary tumours (56% vs. 74%)." (PMID 36561523, 2022). "Here, we provide demonstration of the prognostic capability of ctDNA-based KRAS mutation status in mPDAC using a large cohort consisting solely of patients with metastatic disease treated with gemcitabine and nab-paclitaxel-based therapy." (PMID 36028483, 2022).
metastatic disease (continued). "In this light, we described the loss of KRAS pathogenic mutations from primary to metastatic tumors in a well-defined model of lung-specific oligometastatic disease, allowing a clean genotype/phenotype correlation study." (PMID 35936004, 2022). "The metastatic tumors retained most of the genetic variants found in the original tumors, but some cases had additional CNVs, including copy number gains for the KRAS, AKT3, RICTOR, FGFR, and FANCD2 genes, and copy number losses for the MYC and RAD50 genes." (PMID 34422662, 2021). "On the other hand, synchronous vs metachronous metastatic disease (p=0.039), age > 75 years (p=0.043), and mucinous histology (p=0.008) were more frequent in G12C mutated tumors compared with other KRAS mutations." (PMID 34660299, 2021). "Recently, sotorasib gained approval for second-line use in patients with metastatic disease harboring the KRAS p.G12C mutation." (PMID 35201504, 2021). "Within the metastatic disease setting, the presence of KRAS/NRAS mutations provides resistance to cetuximab and panitumumab, while BRAFV600E mutation predicts response to anti-EGFR targeted therapies in combination with a BRAF inhibitor." (PMID 34201502, 2021). "On multivariate analysis detection of KRAS and metastatic disease were statistically associated with worse PFS." (PMID 35083150, 2021). "Currently, the workup for metastatic disease recommends the investigation of activating mutations in KRAS (exon 2, 3, or 4) or NRAS (exon 2, 3 or 4) and BRAF (V600E), as well MMR status." (PMID 34201502, 2021). "As one study revealed that 97 % of tumors carried mutant KRAS, 18 % of the CTCs were found to carry only the KRAS wild type allele, even those from metastatic tumors." (PMID 33593396, 2021). "The present study was undertaken in order to analyze the mutational trajectories of KRAS in a well-characterized cohort of CRC patients who developed poly- or oligo-metastatic disease." (PMID 33854968, 2021). "Analyzing 19 publications KRAS mutation status turned out to be highly concordant in primary and distant metastatic tumors." (PMID 33002027, 2020). "The authors concluded that there is currently insufficient evidence to definitively state that KRAS wild-type/BRAF-mutated metastatic tumors respond differently to anti-EGFR therapy compared with KRAS wild-type/BRAF wild-type tumors." (PMID 32019056, 2020). "Our results implicate that KRAS mutation status remains consistent in the oncological evolution to metastatic disease." (PMID 33002027, 2020). "In CRC patients, KRAS mutations are present in 45% of metastatic tumors and approximately 15%–37% of early stage tumors and is more often found in pMMR compared to MSI tumors." (PMID 32019056, 2020). "Of the eleven patients with a metastatic disease or local recurrence, five patients showed a KRAS mutation whereas six patients had a KRAS wildtype status." (PMID 33002027, 2020). "Currently KRAS mutation status concordance between the primary and metastatic tumor site has become more and more obvious." (PMID 33002027, 2020). "KRAS mutations and extrahepatic metastatic disease were observed in 26.5% and 10.2% of patients with CRLMs." (PMID 31737121, 2019). "PCR-based Sanger sequencing showed KRAS mutations in metastatic tumor tissue of patients 2 (G12D), 3 (G12A) and 4 (G13D) and a NRAS mutation for patient 8 (G13R “c37G > C)." (PMID 31675944, 2019). "The metastatic tumors showed a higher prevalence (90.99% versus 66.31%) and diversity of KRAS mutation compared with the primary tumors." (PMID 30406144, 2018).
metastatic disease (continued). "Mutational status between primary and metastatic tumors is highly concordant, but KRAS, HER2, and PIK3CA HS values are significantly higher in metastatic tumors than in primary tumors." (PMID 29518290, 2018). "KRAS mutational discordance between primary and paired metastatic tumors was identified in 2 patients (2/16, 13%), whilst BRAF mutation was concordant in the single patient with a BRAF mutant allele." (PMID 29423054, 2018). "In this study, we assessed the prevalence of KRAS genetic alterations, including point mutations, copy number alterations, and gene fusion in both the primary tumors (TCGA) and metastatic tumor samples (MSKCC-IMPACT) at the Pan-Cancer scale." (PMID 30406144, 2018). "The heterogeneity of CRC has been underscored and demonstrated in numerous studies as researchers have highlighted significant differences in the KRAS mutational status between primary vs metastatic tumors." (PMID 29765524, 2018). "It was a smaller study than ours (n = 32/78 with a KRAS mutation in the serum) and they had a more inhomogeneous cohort including rectal cancer (50%) and metastatic disease (14%)." (PMID 28378527, 2017). "KRAS mutations were detected in 41 patients with primary or metastatic tumors and the levels of the plasma mutant KRAS (pmKRAS) were lower than 75%." (PMID 28392479, 2017). "Recently, studies exploring the correlation between KRAS mutational status in primary and metastatic tumors of CRC patients revealed intra-tumor heterogeneity or mutation discordance after anti-EGFR treatment failure in patients with wild type KRAS." (PMID 29100436, 2017). "Cases with matched primary and metastatic tumors harbored identical mutations in both sites (PIK3CA/KRAS and RB1 gene mutations, respectively)." (PMID 26625196, 2016). "Overall, 10 reports of KRAS mutation status concordance between matched primary and metastatic tumours were identified, of which three analysed lymph node metastases." (PMID 26338018, 2015). "Further, the associations of KRAS codon 13 mutation with metastatic disease and codon 12 mutation with mucinous tumour type have also been demonstrated previously." (PMID 24020794, 2013). "KRAS mutational analysis of primary or metastatic tumor tissues is recommended for all MRCRC patients receiving anti-EGFR chemotherapy." (PMID 22876814, 2012). "Our results are generally consistent with previous studies that have reported a high concordance rate of KRAS mutation (about 90%) between primary and metastatic tumors." (PMID 22876814, 2012). "Only one patient carried the same KRAS mutation in both primary tumor and metastatic tumor (case 31)." (PMID 21414214, 2011). "Our data showed that the KRAS mutations were detected in the primary tumor of one adenocarcinoma and also in six metastatic tumors (five squamous cell carcinomas and one adenocacinoma), consistent with those previous reports." (PMID 21414214, 2011). "In predicting DFS, factors such as the number of metastatic tumors, cN stage, KRAS and BRAF mutations, patient age, primary tumor site, CEA levels, neutrophil count, monocyte count, platelet count, and D-Dimer levels were identified as significant predictors for DFS using univariate analysis." (PMID 39991568, 2025). "Notably, although KRAS mutations were relatively at lower rates, the vast majority of KRAS mutations were exon-2 mutations, including patients who presented with non-metastatic disease at the time of diagnosis." (PMID 40940860, 2025). "The univariate Cox regression analysis revealed that the number of metastatic tumors, cN stage, KRAS and BRAF gene mutations, patient age, primary tumor site, CEA levels, neutrophil count, platelet count, and D-Dimer levels exhibited a significance level of P <0.1." (PMID 39991568, 2025).
metastatic disease (continued). "Other disease factors, such as primary tumor laterality, receipt of pre-hepatectomy chemotherapy, and timing of metastatic disease, may impact the prognostic role of KRAS mutations." (PMID 38667294, 2024). "Patients with KRAS mutation (KRAS G12C n = 35, other KRAS n = 74) were younger than patients without KRAS mutations, were all previous or current smokers, and had more often metastatic disease at diagnosis." (PMID 38785486, 2024). "Several groups found significant associations between mutant KRAS–ctDNA positivity and inferior prognosis across the spectrum of disease, including pre-operative patients, those with residual disease post-resection, and those with metastatic disease." (PMID 39409954, 2024). "According to this study, aberrations in EGFR and KRAS were encountered in both primary and metastatic tumors, while certain mutations such as HRAS could only be traced to metastatic tumors." (PMID 38539567, 2024). "From a molecular perspective, specific patterns currently studied mainly in metastatic disease (like mutations of KRAS and NRAS genes) could be a useful tool for selecting high-risk patients." (PMID 39409934, 2024). "Our data also suggest that pre- and post-operative bevacizumab treatment, in addition to metastatic tumor resection, may provide survival benefits in patients with mCRC and KRAS mutations and should therefore be considered in this setting." (PMID 37141400, 2023). "Furthermore, in a phase II trial (NCT03785249), adagrasib also showed clinical efficacy without new safety signals in NSCLC patients with advanced or metastatic tumors harboring KRAS p.G12C mutation." (PMID 37301854, 2023). "Interestingly, tumor cells harboring KRAS G12V upregulate several genes associated with more aggressive or metastatic tumors, including COL1A1, VIM and MUC5B 42–44." (PMID 35995947, 2022). "Moreover, they found that a major imbalance of allelic states of KRAS (KRASMa) favoring the mutant allele over the wild-type allele occurred in only 4% of primary tumors compared to 29% in metastatic disease." (PMID 34805152, 2021). "Analysis of cfDNA from each patient revealed the presence of a canonical KRAS somatic mutation, which was determined by ddPCR and was found to be 38% (21/55) overall; 48% (15/31) in metastatic disease and 25% (6/24) in locally advanced disease, in keeping with other published studies." (PMID 31406261, 2019). "However, KRAS mutant metastatic tumor showed poorer survival versus their KRAS wild-type counterparts (P=4.285 × 10−6), further suggesting the importance of KRAS mutation detection in the clinical management of metastatic tumors." (PMID 30406144, 2018). "We depicted the landscape of somatic KRAS mutation in 7,844 primary tumors and 10,336 metastatic tumors across over 30 types of cancer using the Cancer Genome Atlas (TCGA) and Integrated Mutation Profiling of Actionable Cancer Targets (MSKCC-IMPACT) databases, respectively." (PMID 30406144, 2018). "This suggests that the mutant allele was either lost from the metastatic tumor or the metastatic deposit arose from a KRAS wildtype clone in the primary tumor and highlights the importance of assessing clinically actionable markers in the metastatic rather than primary tumor sample." (PMID 29423054, 2018). "However, so far, only KRAS mutation analysis has been used clinically as a predictive marker for the efficacy of anti-epidermal growth factor receptor antibodies in metastatic disease." (PMID 25426562, 2015). "However, existing evidence indicates that patients with metastatic tumors as well as KRAS mutation show worse prognosis than patients with wild-type KRAS." (PMID 25685149, 2015).
metastatic disease (continued). "Second, we were unable to demonstrate the intra-patient variability of the EGFR or KRAS mutations between primary lesions and metastatic lesions, because the tests for EGFR and KRAS mutations were performed in either the primary tumor or metastatic tumor sample from each patient." (PMID 26081767, 2015). "Further, KRAS codon 13 mutation correlated with metastatic disease (M1) and p27 negativity." (PMID 24020794, 2013). "Although almost 70% of patients with NSCLC present with locally advanced or metastatic disease at the time of diagnosis, KRAS and EGFR mutation status is most commonly assessed only in the primary tumor tissue based on the assumption that primary and metastases are pathologically concordant." (PMID 21414214, 2011). "Additionally, KRAS mutation status was a marker of increased likelihood of disease recurrence (p = 0.0434), as was increased number of liver tumors (p = 0.0071) and multiple sites of extrahepatic metastatic disease (p < 0.0001)." (PMID 39335120, 2024). "The KRAS mutation detection rate in liquid samples might be different for metastatic disease." (PMID 37751775, 2023). "While this could be a random effect, it may also suggest that, at least in the setting of non-metastatic disease/limited tumour burden, tumours with specific KRAS mutations (i.e., G12V) are less likely to release DNA in blood compared to those harbouring different mutations (i.e., G12D)." (PMID 29362371, 2018). "Nine prognostic factors were then identified: metastatic tumor count, cN stage, KRAS and BRAF status, patient age, primary tumor location, neutrophil and platelet counts, and D-Dimer level." (PMID 39991568, 2025). "Positive EGFR mutations, KRAS mutations, and EML4::ALK fusion in metastatic tumors often suggest a lung origin." (PMID 39980562, 2025). "In the metastatic tumor, mTOR, KRAS and MYC were found to be up regulated compared with normal liver tissues (p < 0.05)." (PMID 40566531, 2025). "The largest series to date used the National Cancer Database to identify 1116 patients with KRAS-mutated CRLM who underwent resection of both their primary tumor and metastatic disease." (PMID 38667294, 2024). "More recently, drugs targeting KRAS G12C or HER2 have also improved survival in patients with metastatic disease." (PMID 36879000, 2023). "Both the primary and matched metastatic tumors harbored identical KRAS (3/4) and phosphatase and tensin homolog deleted on chromosome 10 (1/4) mutations, and did not harbor any additional mutations." (PMID 37626765, 2023). "This case also had mutations for APC, KRAS and SMAD4 which were identical in the primary and metastatic tumours." (PMID 37670299, 2023). "Oncologists reported testing for KRAS, NRAS, BRAF, HER2, and mismatch repair deficiency/microsatellite instability in 72%, 65%, 63%, 56%, and 66% of patients with metastatic disease, respectively." (PMID 37682042, 2023). "KRAS G12D and G12V showed the highest variation frequency (43% and 22% in primary tumors, and 47% and 45% in metastatic tumors, respectively)." (PMID 35664782, 2022). "KRAS/LKB1 (STK11) NSCLC metastatic tumors are intrinsically resistant to anti-PD-1 or PD-L1 immunotherapy." (PMID 35210547, 2022). "The currently approved FDA ctDNA clinical tests for metastatic disease are: ‘FoundationOne CDx’, ‘Praxis Extended RAS panel’, ‘Cobas KRAS Mutation Test’, ‘therascreen KRAS RGQ PCR Kit’, ‘Dako EGR pharmDx Kit’, and ‘therascreen BRAF V600E RGQ PCR Kit’." (PMID 33477814, 2021).